MUC3A (mucin 3A, cell surface associated)
Description:
Major glycoprotein component of a variety of mucus gels. Thought to provide a protective, lubricating barrier against particles and infectious agents at mucosal surfaces. May be involved in ligand binding and intracellular signaling.
Synonyms: MUC-3A; MUC3
Tractability: Antibody: its Gene Ontology location is reachable by antibodies, with high confidence; UniProt places it where antibodies can reach, with medium confidence; UniProt predicts a signal peptide or a membrane-spanning region.
Gene: Protein-coding gene on chromosome 7 (100,949,422 to 100,968,348, forward strand). Ensembl gene ENSG00000169894.
Subcellular location: Membrane (Isoform 1); Secreted (Isoform 2); Secreted (Isoform 3); Secreted (Isoform 4); Secreted (Isoform 5)
Subcellular location (Human Protein Atlas): Cell Junctions
Pathways (Reactome):
Disease: Defective C1GALT1C1 causes TNPS; Defective GALNT12 causes CRCS1; Defective GALNT3 causes HFTC
Metabolism of proteins: O-linked glycosylation of mucins; Termination of O-glycan biosynthesis
Immune System: Dectin-2 family
Gene Ontology:
Molecular function: protein binding; extracellular matrix constituent, lubricant activity; extracellular matrix structural constituent
Cellular component: extracellular region; Golgi lumen; membrane; plasma membrane
Genetic constraint (gnomAD): Loss-of-function variants: 97 observed, 88.29 expected, observed/expected ratio (o/e) 1.1, 90% interval 0.93 to 1.3. The synonymous counts are far from expectation, so gnomAD's model fits this gene poorly and the ratio says little. Missense variants: 2,682 observed, 1,698.3 expected, observed/expected ratio (o/e) 1.58, 90% interval 1.53 to 1.63. Synonymous variants: 1,024 observed, 669.66 expected, observed/expected ratio (o/e) 1.53, 90% interval 1.45 to 1.61.
Homologues: Orthologues: macaque MUC3A (81% identical), rat Muc3l1 (36% identical), mouse Muc3a (4% identical). Paralogues in human: MUC17 (24% identical), MUC13 (3% identical).
Diseases named in the same sentence as MUC3A in open-access papers:
MUC3A is named in the same sentence as 57 diseases in open-access papers, as found by Europe PMC text mining. Sharing a sentence is not in itself a finding about the gene and the disease. The quoted sentences say what the papers report.
non-small cell lung carcinoma (6 papers, 2021 to 2025). A group of at least three distinct histological types of lung cancer, including non-small cell squamous cell carcinoma, adenocarcinoma, and large cell carcinoma. "MUC3A mutation is associated with poor overall survival in chronic myeloid leukemia and overexpression of MUC3A enhances the metastasis, which showed poor prognosis in gastric cancer and non-small cell lung cancer." (PMID 40413685, 2025). "MUC3A is highly expressed in non-small cell lung cancer and promotes its progression by activating the NFκB pathway and attenuating radiosensitivity." (PMID 35655161, 2022). "In the currently available studies, MUC3A decreased the sensitivity of radiotherapy for non-small cell lung cancer and reduced the efficacy of targeted therapy by inducing PD-L1." (PMID 35655161, 2022). "Our tissue microarray showed the same results that MUC3A was highly expressed in non-small cell lung cancer." (PMID 33994852, 2021). "Mucin 3A (MUC3A) is highly expressed in non-small cell lung cancer (NSCLC), but its functions and effects on clinical outcomes are not well understood." (PMID 34326691, 2021).
colorectal cancer (5 papers, 1991 to 2024). A primary or metastatic malignant neoplasm that affects the colon or rectum. "Previous research highlighted that MUC3A variants were associated with inflammatory bowel disease and that this gene also promoted the progression of colorectal cancer." (PMID 35886052, 2022). "Mucin 3A (MUC3A) is overexpressed in colorectal cancer (CRC) and associated with poor prognosis, but the related mechanism remains unclear." (PMID 35655161, 2022). "Furthermore, FREM2 mutations may be potential prognostic markers in colorectal cancer, a disease modified by MUC3A, a gene that was mutated in our five patients with HSD." (PMID 35886052, 2022). "MUC3A was the top mutated gene in multiple BRCA cell lines and promoted the progression of colorectal cancer through the PI3K/Akt/mTOR pathway." (PMID 37508580, 2023).
inflammatory bowel disease (5 papers, 2021 to 2023). A spectrum of small and large bowel inflammatory diseases of unknown etiology. "MUC3A variants are mentioned as they are associated with inflammatory bowel disease, and three out of five patients from the study presented gastrointestinal problems." (PMID 38102224, 2023). "MUC3A was enriched in the maintenance of gastrointestinal epithelium and extracellular matrix structural constituent and associated with inflammatory bowel disease." (PMID 34545326, 2021). "Muc3a is a known protein-coding gene associated with inflammatory bowel disease and several cancers, but its role in the FAE brain has not yet been studied." (PMID 36672262, 2023).
lung carcinoma (4 papers, 2020 to 2023). "MUC20 and MUC3A co-mutated at the junction of the tumor and tumor tissues are mucin family genes that are involved in the development of various adenocarcinomas, including lung cancer." (PMID 33133167, 2020). "Favorably, MUC3A is rarely expressed in normal pulmonary epithelial cells, making it been a promising tumor biomarker for lung cancer." (PMID 34326691, 2021). "Our studies provided rationale to target MUC3A combining with TKIs in EGFR-mutant lung cancers." (PMID 33994852, 2021). "Our studies indicated that MUC3A might be a potential target in lung cancer treatment strategies." (PMID 33994852, 2021). "MUC3A is highly expressed in NSCLC cells and rarely expressed in normal pulmonary epithelial cells, making it a promising tumor biomarker for lung cancer." (PMID 33994852, 2021).
colitis (3 papers, 2022 to 2024). Inflammation of the colon. "MUC3A and MUC1 were selected, as MUC3A is one of the most well-understood and predominant transmembrane mucin of HT29-MTX cells and MUC1 is known to have aberrant expression in colitis-like phenotypes." (PMID 38612988, 2024).
idiopathic membranous nephropathy (3 papers, 2020 to 2022). "In idiopathic membranous nephropathy, upregulation of blood and urinary MUC3A circular RNA (circRNA) and various small nucleolar RNAs (snoRNAs) such as SNORA51, SNORA31, SNORA70, SNORA75, and SNORD112 has been reported." (PMID 32849923, 2020).
virus infection (3 papers, 2016 to 2022). "Furthermore, the association of the olfactory receptor gene OR9G9 has recently been related to some viral infectious diseases, while the role of mucin genes (MUC6 and MUC3A), encoding mucin glycoproteins, are well-known factors related to chronic obstructive airway disease." (PMID 29751582, 2018).
clear-cell renal cell carcinoma (2 papers, 2021 to 2022). "For instance, serum MUC3A is a potential diagnostic biomarker for extrahepatic cholangiocarcinoma; high expression of MUC3A is associated with localized clear-cell renal cell carcinoma; bone marrow MUC4 expression had significant prognostic value in acute myeloid leukaemia." (PMID 34828282, 2021). "Abnormal overexpression of MUC3A in clear-cell renal cell carcinoma (ccRcc), breast, pancreatic, gastric, colorectal, appendiceal, and prostate cancer is associated with poor prognosis." (PMID 35038288, 2022).
gastric tumor (2 papers, 2020 to 2023). "There is evidence that the MUC3A gene is involved in the pathogenesis of GC, being aberrantly expressed in gastric tumor cells, and there has also been found an association with the disease severity." (PMID 36833207, 2023).
glioblastoma (2 papers, 2023). The most malignant astrocytic tumor (WHO grade IV). "Among the ten most mutated genes identified by Maftools, MUC3A showed the highest mutation frequency among our samples; however, it exhibited a low frequency (~5%) in glioblastoma TCGA data." (PMID 36980325, 2023).
lymph node metastasis (2 papers, 2021). "Moreover, LUAD patients were sub-grouped into 4 groups by their PD-L1 and MUC3A expression levels, and the increased MUC3A and PD-L1 levels were correlated with increased lymph node metastasis (p < 0.05)." (PMID 33994852, 2021). "We found that high MUC3A expression was a trend to indicate more lymph node metastasis." (PMID 34326691, 2021).
prostate carcinoma (2 papers, 2021 to 2022). A carcinoma that arises from epithelial cells of the prostate gland. "Poor prognosis with abnormal high MUC3A expression has been researched in breast, pancreatic, gastric, colorectal, appendiceal, and prostate cancer." (PMID 34545326, 2021).
adenoma (1 paper, 2025). A neoplasm arising from the epithelium. "Since APC and KRAS are the most frequently mutated driver genes in the adenoma-to-carcinoma sequence, they could be expected to demonstrate alterations more frequently; moreover, the MUC6 and MUC3A mutations were the most frequent, followed by KRAS mutations, principally in TAs and VAs/TVAs." (PMID 40002249, 2025).
Airway obstruction (1 paper, 2023). Obstruction of conducting airways of the lung. "We concluded that MUC3A and MUC3B in large airways may be a marker of disease or may play a role in the pathophysiology of airway obstruction." (PMID 37686350, 2023). "MUC3A and MUC3B mRNA levels were higher in current smokers, regardless of airway obstruction, than in never-smokers." (PMID 37686350, 2023).
chronic bronchitis (1 paper, 2023). A type of chronic obstructive pulmonary disease characterized by chronic inflammation in the bronchial tree that results in edema, mucus production, obstruction, and reduced airflow to and from the lung alveoli. "COPD diagnosis, smoking history, sex, and chronic bronchitis were neither associated with MUC3A nor with MUC3B expression." (PMID 37686350, 2023).
colon cancers (1 paper, 2021). "Robust markers of metaplasia in our study included cathepsin E (CTSE), which has been associated with gastric and colon cancers and previously shown to be upregulated in patients with BAR and EAC, as well as the anion/bicarbonate channel CFTR and PDZ-domain-containing mucins MUC17, MUC3A, and MUC12." (PMID 34412659, 2021).
Constipation (1 paper, 2021). Infrequent or difficult evacuation of feces. "Consistent with that, the subjects recruited in this study all had symptoms of constipation, the SNVs identified in the samples were enriched in the genes associated with gut functions, e.g. the mucin gene (MUC2, MUC3A, MUC4, and MUC5B)." (PMID 33412999, 2021).
emphysema (1 paper, 2023). "Moreover, patients with emphysema had higher MUC3A protein expression in ciliated cells, compared to patients without emphysema." (PMID 37686350, 2023). "MUC3A and MUC3B immunohistochemical expression was equal in all study groups but subjects with emphysema had higher MUC3A expression, compared to those without emphysema." (PMID 37686350, 2023). "Additionally, subjects with emphysema had higher MUC3A protein expression in ciliated cells, compared to subjects without emphysema." (PMID 37686350, 2023). "In addition, patients with emphysema had higher MUC3A expression in ciliated cells, compared with patients without emphysema." (PMID 37686350, 2023).
esophageal cancer (1 paper, 2023). A primary or metastatic malignant neoplasm involving the esophagus. "In summary, these data indicate correlation between the proproliferation and antiapoptotic effects of MUC13 with the expression of GLANT14, MUC3A, MUC1, MUC12 and MUC4 in esophageal cancer." (PMID 37395858, 2023). "In this study, we confirmed that GLANT14, MUC3A, MUC1, MUC12, and MUC4 regulatory factors which related to the O-glycan process were overexpressed and downregulated with MUC13 knockdown in esophageal cancer cells, resulting in insufficient tumor growth and proliferation." (PMID 37395858, 2023).
Hyperglycemia (1 paper, 2023). An increased concentration of glucose in the blood. "According to our data, hyperglycemia alone caused upregulation of a number of genes such as TGFA, CDCA5, MUC3A and C3AR1." (PMID 37511575, 2023).
influenza (1 paper, 2019). An acute viral infection of the respiratory tract, occurring in isolated cases, in epidemics, or in pandemics; it is caused by serologically different strains of viruses (influenzaviruses) designated A, B, and C, has a 3-day incubation period, and usually lasts for 3 to 10 days. "Quantitative real-time RT-PCR analysis of MUC15, MUC13 and MUC3A gene mRNA expression in hNECs infected with seasonal influenza H1N1, H3N2, and B, with uninfected control subjects as baseline (n = 4) and using PGK1 as the internal control." (PMID 31307416, 2019).
lentivirus infection (1 paper, 2021). Virus diseases caused by the Lentivirus genus. "The verification of knock down of MUC3A gene via shRNA lentivirus infection was done by IHC." (PMID 34326691, 2021).
lymphoma (1 paper, 2018). A malignant (clonal) proliferation of B- lymphocytes or T- lymphocytes which involves the lymph nodes, bone marrow and/or extranodal sites. "Until now, no available data have demonstrated that MUC3A is related to lymphoma." (PMID 30106962, 2018).
oral cancer (1 paper, 2025). "Recently, MUC3A has also been associated with the progression of oral cancer." (PMID 40563552, 2025).
pneumonia (1 paper, 2018). An acute, acute and chronic, or chronic inflammation focally or diffusely affecting the lung parenchyma, caused by an infection in one or both of the lungs (by bacteria, viruses, fungi, or mycoplasma.). "Therefore, detection of MUC6 (mucin 6, oligomeric mucus/gel-forming) and MUC3A (mucin 3A, cell surface associated) as associated to pneumonia seems most relevant." (PMID 29751582, 2018).
pulmonary disease (1 paper, 2023). "Thus, MUC3A and MUC3B may present either a surrogate marker of lung function or play a causal role in the pathophysiology of lung diseases." (PMID 37686350, 2023). "This indicates that MUC3A and MUC3B may be biomarkers of pulmonary disease and that more research is needed to elucidate the role of these mucins in the respiratory epithelium." (PMID 37686350, 2023). "MUC5AC is a secretory mucin with a relatively well-described role in the respiratory tract, while MUC3A and MUC3B are membrane-tethered mucins that have not yet been studied in the context of pulmonary diseases." (PMID 37686350, 2023).
renal carcinoma (1 paper, 2023). A carcinoma arising from the epithelium of the renal parenchyma or the renal pelvis. "An association with MUC3A expression and poor prognosis has been associated with gastrointestinal malignancies (e.g., gastric, pancreatic), breast, and renal cancers." (PMID 36382570, 2023).
renal cell carcinoma (1 paper, 2023). "MUC3A encodes for a glycoprotein that is involved in mucin structure in the intestinal tract, while interestingly, its overexpression is linked to poor outcomes in renal cell carcinoma." (PMID 37511575, 2023).
squamous cell carcinoma (1 paper, 2021). A carcinoma arising from squamous epithelial cells. "From the public database, we found that MUC3A levels in LUAD and squamous cell carcinoma were significantly higher than those in normal lung tissues (p < 0.01)." (PMID 34326691, 2021).
tongue squamous cell carcinoma (1 paper, 2025). A squamous cell carcinoma that arises from the tongue. "Another study showed that ZNF717 and MUC3A are mutated in tongue squamous cell carcinoma." (PMID 40563552, 2025).
tumor (18 papers, 2016 to 2025). "For instance, it should be noted that in all patients, the largest number of genetic variants in both tumor and healthy tissue was found in the genes of the mucin family—MUC3A and MUC16." (PMID 36833207, 2023). "The abnormal expression of MUC3A is highly associated with a poor prognosis in many tumor types, although the roles of MUC3A in cancer development are not yet clear." (PMID 35038288, 2022). "IHC of the tumor sections was used to confirm MUC3A knockdown by shRNA lentiviruses, and the xenografts from the mice injected with MUC3A-deficient cells presented significantly less MUC3A and PD-L1." (PMID 33994852, 2021). "We noted an increased tumor mutation burden and a higher frequency of specific known driver mutations when compared to The Cancer Genome Atlas database; we also found novel mutations in MUC3A, MUC5AC, HCAR3, ORT2B, and PABPC." (PMID 36382570, 2023). "In NSCLC, the transmembrane mucin MUC3A—overexpressed in tumor tissues—is regulated by the NF-κB pathway through its interaction with RELA (p65)." (PMID 40655139, 2025). "In NSCLC, elevated levels of MUC3A correlate with increased tumor growth, reduced sensitivity to therapies such as radiation, and the upregulation of immune checkpoint proteins like PD-L1, which facilitate immune evasion by tumors." (PMID 40655139, 2025). "The MUC3A gene is mapped to a mucin cluster located on chromosome 7q22, is a tumor suppressor gene found to be expressed at low levels in a variety of tumors, and is involved in the malignant progression of tumors and in their prognoses." (PMID 35251475, 2022). "In conclusion, knockout of MUC3A inhibited tumor proliferation, invasion, and chemoresistance in CRC via the PI3k/Akt/mTOR signaling pathway." (PMID 35655161, 2022). "MUC3A deficiency significantly suppressed tumor volume, and the combination with AZD-9291 exerted synergistic effect on the reduction of tumor burden." (PMID 33994852, 2021). "It was reported that a conserved TFLK motif and hypoxia tumor microenvironment were attributed to MUC3A expression." (PMID 34326691, 2021). "Similar to the findings in vitro, MMP-2 was notably decreased in the MUC3A-knockdown tumor." (PMID 34326691, 2021). "MUC3A knockdown also inhibited tumor growth in vivo and had synergistic effects with radiation." (PMID 34326691, 2021). "Furthermore, there were six genes (EGR1, MUC20, MUC3A, NBPF19, NOL4L, and OR4L1) that were simultaneously mutated in the tumor tissues and junction tissues." (PMID 33133167, 2020). "By inhibiting MUC3A, the rate of tumor evolvement maybe decreases and improves the effectiveness of existing therapeutics." (PMID 27374181, 2016). "The RT‐qPCR analysis revealed that all target genes (MUC3A, MUC4, MUC13, and MUC16) are significantly overexpressed in tumor samples as compared to control samples." (PMID 41142718, 2025). "The expression profiling of overexpressed MAMs explored the cancer‐specific overexpression of MUC3A, MUC4, MUC13, and MUC16 in tumor samples as compared to control." (PMID 41142718, 2025). "Specifically, three membrane‐bound MUCINs (MUC3A, MUC12, and MUC20) and one atypical mucin (MCAM) were overexpressed in the tumor samples (p < 0.05)." (PMID 34327857, 2021). "Moreover, the EGF-like domain of MUC3A enhances EGFR signaling, forming a feedforward loop that amplifies mucin-TF interactions during tumor progression." (PMID 40655139, 2025). "Surprisingly, tumor size and lymphatic metastasis status failed to correlate with MUC3A expression levels." (PMID 34326691, 2021).